KLF6 (KLF transcription factor 6)
Diseases named in the same sentence as KLF6 in open-access papers (continued):
Sharing a sentence is not in itself a finding about the gene and the disease.
cancer (continued). "Additionally, our study identified six hypoxia-related hub genes significantly associated with KLF6, which could influence rupture in IA or angiogenesis in cancer, further supporting the possibility of KLF6 influencing the hypoxic microenvironment in IA." (PMID 39215680, 2024). "Moreover, the clinical value of KLF6 was assessed at the pan-cancer level." (PMID 38773440, 2024). "Notably, KLF6 is also associated with TMB and MSI in various types of cancer." (PMID 38773440, 2024). "However, whether cancer cell-derived PDGFB is also able to activate mTORC1 activity in KLF6-depleted cells has remained unclear." (PMID 37047421, 2023). "miRNA targeted gene pathway interaction identified BCL7A, BCL2L1, LIN28A, KLF6, GATA6, solute carrier family genes and ZNF genes associated with erythropoiesis, cell cycle regulation, glycosphingolipid biosynthesis, cAMP, cGMP-PKG, mTOR, MAPK and PI3K-AKT signaling pathways and cancer pathways." (PMID 36295630, 2022). "In addition, KLF6 has both growth-suppressive and supportive functions in different cancers." (PMID 35992780, 2022). "Oncogenic features of KLF6 in ccRCC, reported for the first time in this new study, may be an unexpected manifestation of the dual functions of this protein, depending on the type of cancer, but these unexpected results also seem to require verification." (PMID 34681854, 2021). "The oncogenic features of KLF6 in ccRCC, reported for the first time in a new study, may be an unexpected manifestation of the dual functions of this protein, depending on the type of cancer, but these unexpected results also need to be verified." (PMID 34681854, 2021). "In addition, promoter hypermethylation and suppression by the noncoding RNAs and microenvironment factors could also result in KLF6 downregulation in cancer." (PMID 32998281, 2020). "Interestingly, KLF6 modulation in cancer cells potentially alters cell cycle progression." (PMID 24378751, 2013). "While Program-1 was enriched with genes from a pan-cancer EMT program, it also notably included epithelial differentiation genes such as CDH1, IRF6, JUP, KLF6, and TJP2." (PMID 40777467, 2025). "In conclusion, cancer cell-derived PDGFB can mediate mTORC1 signalling pathway activation in ccRCC, further consolidating the link between the KLF6-PDGFB axis and the mTORC1 signalling pathway activity in ccRCC." (PMID 37047421, 2023). "The accessibilities of the KLF6 and NRF1 motifs were also increased in these cancers, further supporting enhanced activity of these TFs." (PMID 37914932, 2023). "Genes such as PYGM, BMF, MBNL3, DENND6A, REEP5, KLF6 and ITM2C are potentially regulated by circYPEL2 and involved in cancer-specific pathways, which are needed to be validated in further studies." (PMID 35052380, 2021). "Specific isoforms of CD44, ENAH actin regulator (ENAH), Kruppel-like factor 6 (KLF6), recepteur d’Origine nantais (RON) tyrosine kinase, and Rac family small GTPase 1 (RAC1) can promote cancer cell invasion and migration." (PMID 34771719, 2021). "Combination with ten cancer types in pan-cancer, four mRNAs (PBX3, KLF6, ARHGAP1, ST3GAL2) were selected out." (PMID 32519740, 2020). "Studies have shown changes in the expression of MUTYH, KLF6, KLF4 and WNT1 genes in various cancers." (PMID 31724937, 2019). "KLF6 is frequently inactivated in HCC and, when overexpressed in carcinoma-derived cells, interacts with cyclin D to disrupt cyclin/CDK complexes, to redistribute p21 to CDK2, which promotes G1 cell cycle arrest." (PMID 30774659, 2019). "Our observation that KLF-6 SV1 expression was highly significantly lower in CLL leukemic cells compared to T cells might be interesting as overexpression of KLF6-SV1 in human cancer cells may accelerate cancer progression and metastasis in animal models as well as in human cancer." (PMID 29432497, 2018). "The PCC between KLF6 and RP11-203J24.8 was 0.71 (P = 3.09E-10) in normal samples, but showed a sharp decrease (PCC = 0.188, P = 2.15E-5) in the cancer group." (PMID 29340074, 2017).
cancer (continued). "Among the genes upregulated in GFPHigh cells are cytokines (IL-6, IL-8, or TNF) and transcription factors (KLF6, ATF3, SNAI2) that have been previously related with cancer stemness, cellular plasticity, or both." (PMID 25414831, 2014). "Similar to the inactivation of KLF6, KLF4 was shown to undergo promoter methylation and LOH in several cancer types." (PMID 22937066, 2012). "The results begin to mechanistically explain, at least in part, the opposing functions of KLF6 and KLF6-SV1 in cancer." (PMID 20844588, 2010). "SDC4high CSCs exhibited high expression of genes such as KLF6, ATF3, and CXCL2, with Kyoto Encyclopedia of Genes and Genomes (KEGG) enrichment analysis revealing their involvement in TNF signaling, MAPK signaling, apoptosis, and cancer development." (PMID 39107908, 2024). "KLF6 function is abrogated in human cancers owing to increased AS that yields a dominant-negative isoform, KLF6 SV1, which antagonizes full-length KLF6-mediated growth suppression, presumably by promoting KLF6 degradation." (PMID 35008179, 2021). "Single-Cell Regulatory Network Inference and Clustering (SCENIC) analyses showed that KLF6 was most significantly upregulated, while EGR1 was most significantly downregulated in GGN-ADC-derived cancer cells when compared with SADC cancer cells based on the area under the curve (AUC) scores." (PMID 33083004, 2020). "An array of mutations in splicing cis-acting sequences include those of LKB1 (liver kinase B1), KIT (v-kit Hardy-Zuckerman 4 feline sarcoma viral oncogene homolog), CDH17 (cadherin 17), KLF6 (Kruppel-like factor 6) and BRCA1 (breast cancer gene 1) in many types of cancers." (PMID 32905346, 2020). "Despite its clear growth regulatory activity in hepatic metabolism and cancer, there are no studies evaluating the role of KLF6 in liver regeneration and hepatocyte proliferation." (PMID 28808340, 2017). "KLF6 has been reported to upregulate p21 and ATF3, but suppress PTTG1 expression in cancer cells." (PMID 28572744, 2017). "Moreover, numerous examples of cancer-relevant genes affected at the splicing level (e.g. ANXA7, GLI1, MAX, KLF6) have been reported in GBM." (PMID 27287018, 2016). "Here, platelet TGFβ1 is a general driver of cancer cell epithelial-to-mesenchymal transition (EMT) via activation of the Smad2/3 and NF-kB pathways, and of HCC growth both in vitro and in vivo, where it also suppresses cancer cell Krueppel-like factor 6 (KLF6) expression." (PMID 38116017, 2023). "Since KLF6 was found to be either downregulated or inactivated in these cancer types, direct KLF6 targeting for cancer therapeutic purposes might not be a viable option." (PMID 32998281, 2020). "A uniquely enriched pathway of all five PCGs (FSTL3, KLF6, MLF1, NR4A3, and SDC4) was “Transcriptional misregulation in cancer” (P = 0.048), suggesting that those five PCGs and their regulating lncRNAs may play roles in transcriptional regulation levels in THCA." (PMID 29340074, 2017). "For targets of lncRNA RP11-203J24.8, we found no KEGG pathways enriched, and only one enriched GO term: “intracellular signal transduction” (P = 0.023); its target KLF6 was reported as a cancer driver gene that also showed importance in thyroid normality maintenance." (PMID 29340074, 2017).
cancer (continued). "Interestingly, cancer exosomes, but not normal exosomes, modulated expression of matrix remodelling (EFEMP1, DDK3, SPARC), cell cycle (EEF2K), membrane remodelling (LAMP2, SRPX), differentiation (SPRR2E), apoptosis (CTSC), transcription/translation (KLF6, PUS7)." (PMID 30008265, 2018).
infection (13 papers, 2011 to 2025). The state of being infected such as from the introduction of a foreign agent such as serum, vaccine, antigenic substance or organism. "On the other hand, infection (the SFV group) significantly upregulated M1-linked TFs Stat1, Irf9 and Klf6 expression, as well as M2-linked Stat3 expression." (PMID 40547518, 2025). "For EB staining, the permeability of the blood–brain barrier in brain tissues of ICH rats was reduced after the infection of sh-KLF6." (PMID 34149393, 2021). "In the presence of sh-SIRT5, the apoptosis rate and the degeneration of hippocampal neurons in ICH rats were diminished by infection with sh-KLF6." (PMID 34149393, 2021). "Additional pro-inflammatory markers in the NHP liver dataset included enriched Klf6, Stat1 and Irf1, as well as Il23 in late-stage infection." (PMID 29724035, 2018). "To illuminate the function of KLF6 in SC apoptosis, we established a stable RSC96 cell line overexpressing KLF6 through infection with a lentivirus vector (pGC-FU-GFP-LV)." (PMID 24324791, 2013). "In the present study we have shown that indeed, KLF factors like KLF6 play an essential role during infection by regulating the expression of TGF-β gene during RSV infection." (PMID 21849067, 2011). "In contrast, there was a greater activation of genes such as TNF-α, IL1A, IL8, JUN, ERRFI1 and KLF6 after infection with N. lactamica relative to N. meningitidis." (PMID 22028815, 2011). "We identified distinct activation of IL-8 signaling and neutrophil degranulation pathways regulated by NF-κB and KLF6 in FIP infection condition, providing evidence that neutrophil-mediated inflammation plays a central role in disease progression and resolution." (PMID 40514753, 2025). "Hippocampal neurons after the infection of sh-KLF6 were exposed to 20 μM OxyHb." (PMID 34149393, 2021). "On the other hand, factors associated with memory development (FOS, KLF6) were upregulated with vaccination but not asymptomatic infection." (PMID 34935643, 2021). "We also detected KLF6 protein expression among three groups, the results showed that ART treatment could increase KLF6 expression in vivo, but LV-shKLF6 infection inhibited the effect, suggesting that the KLF6 knockout model was successfully established." (PMID 31723124, 2019). "Furthermore, the P. aeruginosa T3SS also induces the production of reactive oxygen species (ROS) during infection and these compounds can induce KLF6 alternative splicing." (PMID 25010049, 2014). "Furthermore, some regulatory targets of KLF6 are known to have roles in the immune response to infections." (PMID 25010049, 2014). "The role of KLF6 in infections is currently less clear than that of KLF2." (PMID 25010049, 2014). "Interestingly, the reduction in viral titer was similar to that was observed following infection of KLF6 silenced cells." (PMID 21849067, 2011). "Moreover, TGF production is required for efficient RSV infection and thus, KLF6 is also required for efficient RSV infection by virtue of KLF6 dependent TGF production during infection." (PMID 21849067, 2011). "In order to investigate the effect of statins on the expression of infection-responsive, immunomodulatory genes, 5 genes previously shown to be induced during P. aeruginosa infection were selected for analysis; KLF2, KLF6, IL-8, TLR5 and CCL20." (PMID 25010049, 2014). "Under conditions of infection with WT V. vulnificus, HT-29 cells upregulated KLF2, KLF4, and KLF6 and downregulated NLRP3, TLR4, and CXCR4, suggesting that the MARTX toxin interrupts inflammatory responses, NF-κB signaling, and mitogen-activated protein kinase (MAPK) signaling in infected cells." (PMID 32817457, 2020). "Previous studies have shown that Kruppel-like factor 6 (KLF6) could function as a trans-activator of TGF gene; however, whether KLF members play a role during infection is unknown." (PMID 21849067, 2011).
inflammation (2 papers, 2022 to 2024). Aberrant reaction of the microcirculation characterized by movement of fluid and leukocytes from the blood into extravascular tissues. "Future studies should focus on investigating the specific KLF6 regulatory mechanism during pulp inflammation and reparative dentin formation." (PMID 35422483, 2022).
kidney diseases (2 papers, 2019 to 2020). "Although several KLF members including KLF2, KLF4, KLF6, and KLF15 in glomerular endothelial cells or podocytes have been linked to kidney diseases, all these reported KLF members serve as renal protectors." (PMID 30948420, 2019). "KLF6 has been reported to participate in proinflammatory gene expression in kidney diseases." (PMID 32157506, 2020).
bacterial infections (1 paper, 2014). "While our results confirm P. aeruginosa induction of wtKLF6 expression, the expression of KLF6 splice variants in the context of bacterial infections has never been characterised." (PMID 25010049, 2014). "While to date, it has not been characterised, it is likely that KLF6 does play a role in bacterial infections, as it is upregulated by S. aureus and P. aeruginosa, and can promote the apoptosis of cells infected with respiratory syncytial virus and influenza A." (PMID 25010049, 2014).
hematopoietic diseases (1 paper, 2013). "Our results suggest that drugs that increase the activities of KLF6 may inhibit the transcription of PTTG1 and have the potential to be used as a therapeutic tool for hematopoietic diseases." (PMID 23977008, 2013).
prostate (1 paper, 2008). "This analysis revealed strong correlations between c-MYC and the prostate tumor suppressor Kruppel-like factor 6 (KLF6) gene." (PMID 18190704, 2008).
KLF6 also shares sentences with these, for which no sentence is quoted: cardiovascular diseases (4 papers); colorectal tumors (4); Arthritis (2); esophageal cancer (2); liver cirrhosis (2); thyroid cancer (2); viral infection (2); acute lung injury (1); adenocarcinoma (1); allergic rhinitis (1); Alzheimer disease (1); anemia (1); autism spectrum disorder (1); Cardiomyopathies (1); cholestasis (1); chronic kidney disease (1); chronic lymphocytic leukemia (1); colitis (1); colon adenocarcinoma (1); Crohn disease (1); demyelinating disorders (1); dyserythropoietic anemia (1); epilepsy (1); epithelial dysplasia (1); esophageal squamous cell carcinoma (1); glomerulonephritis (1); head and neck squamous cell carcinoma (1); heart disease (1); hepatotoxicity (1); HIV-associated nephropathy (1).
A further 32 diseases each share a sentence with KLF6 in 1 paper.